BTAF1 (B-TFIID TATA-box binding protein associated factor 1)
Description:
Regulates transcription in association with TATA binding protein (TBP). Removes TBP from the TATA box in an ATP-dependent manner.
Synonyms: TAF-172; TAF172; TAFII170; MOT1; TAF(II)170
Tractability: PROTAC: ubiquitination databases record sites on it; its protein half-life has been measured.
Gene: Protein-coding gene on chromosome 10 (91,923,770 to 92,031,437, forward strand). Ensembl gene ENSG00000095564.
Subcellular location: Nucleus
Subcellular location (Human Protein Atlas): Nucleoplasm; Vesicles
Gene Ontology:
Molecular function: ATP-dependent activity, acting on DNA; transcription coregulator activity; ATP binding; ATP hydrolysis activity; DNA binding; TBP-class protein binding
Biological process: negative regulation of chromatin binding; negative regulation of DNA-templated transcription
Cellular component: nucleoplasm; nucleus
Genetic constraint (gnomAD): Loss-of-function variants: 32 observed, 202.16 expected, observed/expected ratio (o/e) 0.16, 90% interval 0.12 to 0.21. The upper end of that interval is the gene's LOEUF score, 0.21, which puts it in group 1 of 6, group 1 being the genes least tolerant of losing a copy. Missense variants: 1,501 observed, 2,127.7 expected, observed/expected ratio (o/e) 0.71, 90% interval 0.68 to 0.74. Synonymous variants: 686 observed, 727.15 expected, observed/expected ratio (o/e) 0.94, 90% interval 0.88 to 1.
Homologues: Orthologues: chimpanzee BTAF1 (100% identical), macaque BTAF1 (99% identical), dog BTAF1 (98% identical), pig BTAF1 (98% identical), rabbit BTAF1 (98% identical), guinea pig BTAF1 (97% identical), mouse Btaf1 (96% identical), rat Btaf1 (96% identical), tropical clawed frog btaf1 (82% identical), zebrafish btaf1 (78% identical), Drosophila melanogaster Hel89B (48% identical), Caenorhabditis elegans btf-1 (27% identical). Paralogues in human: EP400 (16% identical), SMARCA2 (15% identical), SMARCA4 (15% identical), ERCC6 (14% identical), SRCAP (14% identical), CHD7 (14% identical), CHD9 (13% identical), ATRX (13% identical), CHD8 (13% identical), INO80 (13% identical), CHD1 (12% identical), CHD2 (12% identical), and 18 more.
Diseases named in the same sentence as BTAF1 in open-access papers:
BTAF1 is named in the same sentence as 5 diseases in open-access papers, as found by Europe PMC text mining. Sharing a sentence is not in itself a finding about the gene and the disease. The quoted sentences say what the papers report.
epilepsy (1 paper, 2022). A brain disorder characterized by episodes of abnormally increased neuronal discharge resulting in transient episodes of sensory or motor neurological dysfunction, or psychic dysfunction. "Hence, AEDs exerted a therapeutic effect on vasogenic epilepsy derived from endothelial CDK5 loss, which results in downregulating epilepsy‐related Phka1 and Btaf1 and upregulating synaptic function‐related Grin1 and Magt1." (PMID 35770064, 2022). "The RT‐PCR results suggested that the mRNA levels of Btaf1, Phka1, and Nav1, which possess a strong correlation with epilepsy, were upregulated significantly." (PMID 35770064, 2022). "Together, the mRNA levels of Btaf1, Phka1, Nav1, and Magt1 were related to epilepsy." (PMID 35770064, 2022). "Moreover, to clarify the effects of AEDs on the mRNA levels of epilepsy‐related and synapse‐related proteins in Cdh5‐CreERT2;CDK5f/f mice, the mRNA levels of Btaf1, Phka1, Nav1, Bdnf, Magt1, and Grin1 were confirmed by qRT‐PCR." (PMID 35770064, 2022). "Accordingly, changes of synapse‐related gene (Phka1, Btaf1, Magt1, and Grin1) and aberrant alternation of NMDA receptors, PSD95, phosphorylation of CaMKII were found in the hippocampus of spontaneous epilepsy mice." (PMID 35770064, 2022).
BTAF1 also shares sentences with these, for which no sentence is quoted: cancer (2 papers); COVID-19 (1); iron-deficiency (1); virus infection (1).